EPCAM (epithelial cell adhesion molecule)
Diseases named in the same sentence as EPCAM in open-access papers (continued):
Sharing a sentence is not in itself a finding about the gene and the disease.
breast carcinoma (continued). "Indeed, EPHB6 presence strongly enhanced expression of EpCAM, which was previously characterised as breast cancer TIC marker." (PMID 29700392, 2018). "Healthy donor blood spiked with cells of the prostate cancer cell line PC3 (1.0 × 104 EpCAM antigens, average size 17.7 μm) and the breast cancer cell line MDA-MB-231 (1.5 × 104 EpCAM antigens, average size 15.6 μm) were tested for recovery of EpCAMhigh and EpCAMlow cells." (PMID 30479699, 2018). "EpCAM selection could enrich certain populations of breast cancer subtypes that possess low tumorigenicity." (PMID 29484537, 2018). "Recent reports showed that EpCAM selection results in the loss of claudin-low cell population, indicating that EpCAM is not a universal marker of all breast cancer cells." (PMID 29484537, 2018). "CD44 is used as a CSC marker for breast cancer and EpCAM is used as a CSC marker for HCC." (PMID 29298343, 2018). "Similarly, cancer cell markers such as EpCAM can be induced in MSCs after 72 h of co-culture with breast cancer cells." (PMID 29515946, 2018). "In this study, dual-color fluorescence observations for two kinds of membrane proteins, EGFR and EpCAM, were detected with a plasmonic chip by using surface plasmon-enhanced fluorescence microscopy in two kinds of breast cancer cell lines, MDA-MB-231 and MCF-7." (PMID 29257118, 2017). "The CellSearch system, as an approved method to test CTCs, depends on the expression of EpCAM and greatly limited the positive rate of CTCs in some epithelium-originated solid tumors like breast cancer and pancreatic cancer for the reason that the expression of EpCAM was reduced during EMT." (PMID 28333072, 2017). "EpCAM-based assay is unable to capture EMT CTCs due to the loss of epithelial features in those cells, but CTCs expressing EMT and epithelial markers can be detected in breast cancer patients using the size-exclusion enrichment method." (PMID 27706044, 2016). "Moreover, we found that NEAT1 upregulation is required for the BRCA1-deficiency-driven effect on increasing the EpCAM+BCSC population and enhancing malignancies of breast cancer cells." (PMID 27556296, 2016). "Multiple markers including CD44, CD24 and EpCAM are used to identify breast cancer stem cells." (PMID 27340862, 2016). "The recent discovery of EpCAM involvement in cell signaling and breast cancer invasion suggests that its vectorization by MPs could contribute to carcinogenesis." (PMID 26689993, 2016). "For that, we selected a breast cancer cell line with low EpCAM expression (MDA-MB-231)." (PMID 27711186, 2016). "In orthotopic xenografts of EpCAM+ and EpCAM- breast cancer cell lines, clear correlations between tumor size and CTC number were observed for both MDA-MB-231 and SUM-149 xenografts, supporting the independence of our CTC capture methodology from cell surface marker expression." (PMID 27501846, 2016). "Based on these finding, cancer stem cell markers and EMT markers could be useful for capturing CTCs from EpCAM-low expressing breast cancer cells." (PMID 27013581, 2016). "EpCAM is the legacy marker for recovery of CTC in breast cancer." (PMID 27049831, 2016). "In breast cancer, the prognostic impact of EpCAM expression depends on breast cancer subtype." (PMID 26296970, 2015). "Epithelial cell adhesion molecule (EpCAM) is a glycosylated, type I transmembrane protein, which is overexpressed in various neoplasms such as breast cancer, hepatocellular carcinoma (HCC), glioma, and colorectal cancer, and is used as a diagnostic and prognostic marker." (PMID 26356670, 2015). "We also explored the role of EpCAM in the progression of breast cancer." (PMID 26356670, 2015). "CTC subsets were selected for EpCAM negativity but positivity for CD44+/CD24− stem cell signature; along with combinatorial expression of uPAR and int β1, two markers directly implicated in breast cancer dormancy mechanisms." (PMID 26631983, 2015). "EpCAM expression was confined to the membrane of breast cancer cells in all cases." (PMID 26356670, 2015).
breast carcinoma (continued). "In addition, 76.7% (92/120) of breast cancer specimens were positively stained with anti-EpCAM, according to our criteria." (PMID 26356670, 2015). "Interestingly, the first report on grafting human-derived breast cancer CTCs in xenograft assays indicated that the putative metastasis-initiating cells expressed EpCAM, although at a reduced level." (PMID 25398926, 2015). "In total, in 20 out of 29 EpCAM-depleted fractions (69%) from 25 metastatic breast cancer patients additional EpCAMneg CTCs could be identified [range of 1–24 CTCs per sample] applying Trop2, CD49f, c-Met, CK8 and/or HA magnetic enrichment." (PMID 26695635, 2015). "These nanoprobes not only possess a narrow-band emission peaked at 698 nm under excitation at 254 nm with excellent NIR long afterglow properties and low cytotoxicity but also possess targeting capability toward breast cancer cells (MCF7) which overexpressed EpCAM antigen." (PMID 30464964, 2015). "Additionally, it has been recently recognized that only EpCAM-negative CTCs in breast cancer patients possess enhanced metastasizing potential to brain, though phenotypic existence of EpCAM on metastasis-initiating cells (MICs) among CTC has been demonstrated." (PMID 26718583, 2015). "Furthermore, si-EpCAM-mediated invasion and metastasis of breast carcinoma cells required the downregulation of matrix metalloproteinase-9 (MMP-9) through inhibition of this signaling pathway." (PMID 26356670, 2015). "Here we present an enrichment strategy combining different antibodies specific for surface proteins and extracellular matrix (ECM) components to capture an EpCAMlow/neg cell line and EpCAMneg CTCs from blood samples of breast cancer patients depleted for EpCAM-positive cells." (PMID 26695635, 2015). "We next used a transwell assay to determine whether EpCAM could affect the ability of breast cancer cells to migrate and invade." (PMID 26356670, 2015). "In addition, EpCAM is highly expressed in MBCs, including the sites of liver metastases, compared to unmatched, surgically resected primary breast cancers." (PMID 25885919, 2015). "In the current study we sought to establish whether an EpCAM based IE/FACS CTC assay can capture the full spectrum of breast cancer subtypes." (PMID 26556851, 2015). "Collectively, our studies demonstrated that MMP-9 may be an effector of breast cancer progression and metastasis mediated by EpCAM." (PMID 26356670, 2015). "We hypothesized that CTC capture using EpCAM based gating is feasible for most breast cancer subtypes." (PMID 26556851, 2015). "In addition, EpCAM expression in advanced-stage (III) breast cancer tissue was significantly higher than that in early-stage tissue (I, II)." (PMID 26356670, 2015). "The in vitro studies on functional role of EpCAM in breast cancer cell lines demonstrated that transfection of EpCAM resulted in increased nuclear accumulation of β-catenin in MDA-MB-231EpCAM and upregulated Wnt reporter assay activity in Hs578TEpCAM cells suggesting activation of Wnt pathway." (PMID 25265904, 2014). "Isolation efficiency of the cancer cells was independent of cell surface markers such as EpCAM and growth receptors in all DEP methods and EpCAM-negative as well as “triple negative” breast cancer lines were collected with the same efficiency as EpCAM-positive and receptor-positive types." (PMID 24662940, 2014). "In our previous study, we found that EpCAM promoted EMT in breast cancer cells." (PMID 25019346, 2014). "Although EpCAM overexpression in breast cancer is correlated with aggressive behavior and decreased overall survival of patients, functions and effects of EpCAM overexpression in normal mammary epithelial cells, i.e. healthy tissue have not been described so far." (PMID 23758908, 2013).
breast carcinoma (continued). "However, further studies are still needed to identify the underlying molecular mechanisms responsible for EpCAM overexpression in the context of TGF-β/Wnt signaling and breast cancer development." (PMID 23758908, 2013). "EpCAM staining with our aptamer showed superior results when compared to the antibody in both human xenograft tumors via fluorescently labeled aptamer and in primary human breast cancers using chromogenic staining." (PMID 23460885, 2013). "Due to its high expression in breast cancer tissue, EpCAM has emerged as an attractive target for treatment of breast cancer patients and recent studies with the humanized EpCAM antibody Adecatumumab showed already promising results in patients with EpCAM overexpression." (PMID 23758908, 2013). "Moreover, the approval by the European Union in 2009 of the EpCAM-specific antibody Catumaxomab, adds a therapeutic option also in breast cancer patients with peritoneal carcinomatosis and malignant ascites." (PMID 23758908, 2013). "Therefore, the fact that EpCAM has a dual role in tumorigenesis should be given consideration when planning EpCAM-targeted therapies in breast cancer patients." (PMID 23110550, 2012). "Moreover, in breast carcinoma EpCAM has been reported to be upregulated in large metastases as compared with the matched primary tumor." (PMID 23110550, 2012). "Most importantly, all these findings might even have a clinical impact since EpCAM-based targeting agents (i.e. catumaxomab) are now available for therapeutic use also in breast cancer patients." (PMID 23110550, 2012). "Based on our previous analysis on EpCAM expression in epithelium- and mesenchyme-like breast carcinoma cell lines we selected two EpCAMlow cell lines for inducible lentiviral overexpression studies, i.e. MDA-MB-231 and Hs578t breast carcinoma cells, both with a mesenchymal cancer phenotype." (PMID 23110550, 2012). "T47D and MCF7 cell lines derived from breast cancer showed medium levels of EpCAM mRNA expression." (PMID 22590529, 2012). "In addition, experimental data suggest that normal-like breast cancer cells are less efficiently captured by an EpCAM-based approach, resulting in a lower sensitivity of this assay." (PMID 22894854, 2012). "EpCAM+ breast cancer and hepatocellular carcinoma showed the CSCs or CPCs phenotype." (PMID 23213278, 2012). "c-Jun expression is able to efficiently rescue AP-1 transcription factor activity (data not shown) and invasion, suggesting that the AP-1 protein subunit c-Jun is a key downstream mediator of EpCAM biology, contributing to EpCAM-dependent breast cancer invasion." (PMID 22132731, 2011). "Since EpCAM signaling and function has been studied primarily in EpCAM-positive breast cancer cell lines with siRNA-based knockdown, we aimed to generate overexpression breast cancer cell lines and characterize these cell line models by analysing migration, proliferation and transcriptional changes." (PMID 21281469, 2011). "In functional rescue experiments, we demonstrate that forced overexpression of c-Jun is capable of rescuing breast cancer invasion following specific ablation of EpCAM, confirming that AP-1 is a key downstream mediator of EpCAM-dependent breast cancer invasion." (PMID 22132731, 2011). "To confirm the impact of EpCAM on breast cancer invasion in vivo, and to establish a functional rescue/gain-of-function model system for mechanistic studies, we generated stable breast cancer cell lines with specific ablation of EpCAM expression using EpCAM-specific lentiviral shRNA constructs." (PMID 22132731, 2011). "So far little data exist on EpCAM signaling in breast cancer." (PMID 21281469, 2011). "Taken together, these findings confirm the hypothesis that EpCAM expression modulates breast cancer invasion, with increased EpCAM expression and/or signaling associated with increased breast cancer invasion." (PMID 22132731, 2011). "In this study we focused on the role of EpCAM in breast cancer invasion." (PMID 22132731, 2011).
breast carcinoma (continued). "To directly assess the functional contribution of AP-1 in EpCAM-mediated breast cancer invasion, we specifically ablated EpCAM expression in CA1a breast cancer cells, and then rescued AP-1 transcription factor activity using a constitutively active c-Jun genetic construct." (PMID 22132731, 2011). "Our studies confirm the importance of the extracellular domain of EpCAM in EPCAM signaling; addition of recombinant extracellular EpCAM rescues breast cancer invasion, AP-1 transcription factor activity, and c-Jun phosphorylation in a dose-dependent fashion following specific ablation of EpCAM." (PMID 22132731, 2011). "Moreover, we identify a novel tumor promoting mechanism of these cells that is enhanced upon exposure to PGE2: the ability to secrete factors (such as IL-6) that are essential for the expansion of CD44+/CD24−/EpCAM+ breast cancer cells." (PMID 21957456, 2011). "Despite the central role of AP-1 as a regulator of invasion, our studies do not exclude the possibility that other signaling pathways are modulated by EpCAM, and may also contribute to the regulation of invasion in breast cancer." (PMID 22132731, 2011). "Only few commercially available immortalized human breast cancer cell lines lack EpCAM expression." (PMID 21281469, 2011). "We have shown that the RT-qPCR-based multi-marker analysis using the six genes: CCNE2, DKFZp762E1312, EMP2, MAL2, PPIC, or SLC6A8 more than doubled the number of positive patients with recurrent breast cancer compared to the analysis of hMAM or EpCAM gene expression alone." (PMID 21129172, 2010). "The panel of six genes was found superior to EpCAM and hMAM for the detection of circulating tumor cells in the blood of breast cancer, and they may serve as potential markers for CTC derived from endometrial, cervical, and ovarian cancers." (PMID 21129172, 2010). "All 16 breast cancer cell lines were analyzed for the expression of EpCAM, CD24, and CD49f to determine whether the same four differentiation states present within human breast tissues were retained in cultured lines." (PMID 20964822, 2010). "Furthermore, the enhanced EpCAM expression could be considered as a poor prognostic marker in breast carcinomas." (PMID 40017594, 2025). "Thus, similar biases between EpCAM and Trop2 could also account for EpCAM KD favoring wetting and Trop2 having the opposite effect in these breast cancer lines." (PMID 39572744, 2025). "Hence, EpCAM-positive CTCs have been used as a prognostic biomarker in patients with various cancer types, including lung cancer, hepatocellular carcinoma, prostate cancer, neuroendocrine cancer, breast cancer, and colorectal cancer." (PMID 38791091, 2024). "In their design, Epithelial cell adhesion molecule (EpCAM) and human epidermal growth factor receptor 2 (HER2) expressed on the tumor‐derived extracellular vesicles are selected as biomarkers for the identification of breast cancer (BC) cells associated with this." (PMID 40626205, 2023). "Thus, N-glycosylation of EpCAM has extremely important physiological effects in breast cancer, which may also apply to other cancer types such as liver cancer." (PMID 36990999, 2023). "Sections of end-stage tumors from each of the four breast cancer mouse models and normal mammary glands were stained for fibroblasts using antibodies against PDGFRβ, αSMA and vimentin; for collagen fibers by Masson Trichrome and for epithelial cells using antibodies against E-cadherin and EpCAM." (PMID 36635273, 2023).
breast carcinoma (continued). "We describe a blood-based breast cancer detection test based on functional enrichment of breast-adenocarcinoma-associated circulating tumor cells (BrAD-CTCs) and their identification via multiplexed fluorescence immunocytochemistry (ICC) profiling for GCDFP15, GATA3, EpCAM, PanCK, and CD45 status." (PMID 35884402, 2022). "Additionally, in a case series of 100 early stage breast cancer, it was found that patients with EpCAM-enriched CTCs overexpressing TWIST1 and showing a stem cell profile, defined as CD44high/CD24−/low and ALDH1high/CD24−/low, had significantly reduced disease-free and overall survival." (PMID 36428760, 2022). "Neoadjuvant and salvage chemotherapy increased EpCAM negative, EMT positive CTCs in breast cancer patients, suggesting that the loss of EpCAM expression in CTCs may enhance chemotherapy resistance." (PMID 34209658, 2021). "Therefore, the expression of EpCAM should be further clarified in breast cancer metastasis." (PMID 31443698, 2019). "Additionally, we used EpCAM as a selective marker for breast cancer cells." (PMID 29515946, 2018). "Importantly, only 4 of 24 breast cancer patients (16.6%) had only EpCAM-positive CTCs." (PMID 27013581, 2016). "However, the role of EpCAM in tumor growth and the mechanism by which EpCAM promotes the metastasis of breast cancer are currently unknown." (PMID 26356670, 2015). "In addition, we investigated whether the Ras/Raf/ERK signaling pathway and MMP-9 played crucial roles in the promotion of growth and invasiveness of breast cancer cells mediated by EpCAM." (PMID 26356670, 2015). "In addition, transformation of human EpCAM+/CD10−/CD49f + luminal progenitors derived from reduction mammoplasties established tumors with features similar to basal-like breast cancer, including reduced ESR1 and greater K14 expression than tumors derived from differentiated luminal cells." (PMID 26429062, 2015). "Epithelial cell adhesion molecule (EpCAM) is a type I transmembrane protein that is expressed in the majority of normal epithelial tissues and is overexpressed in most epithelial cancers including breast cancer, where it plays an important role in cancer progression." (PMID 26356670, 2015). "Therefore, EpCAM may be a potential candidate as a chemosensitizer in the management of breast cancer." (PMID 25019346, 2014). "Further, significantly higher numbers of CTCs could be detected using an EpCAM independent detection method compared to EpCAM based enrichment technology (69.2% vs. 42.3%) in breast cancer patients, suggesting that a mixture of EpCAM positive and EpCAM negative tumour cells circulate in the blood." (PMID 22591372, 2012). "Further investigations on the interaction of EpCAM with SFRP1 and TCF7L2 and on additional factors, which may be causal for changes upon EpCAM overexpression, will help to characterize unique molecular properties of EpCAM-positive breast cancer cells." (PMID 21281469, 2011). "Importantly, those observations could be confirmed only partially with the weakly EpCAM-positive non tumourigenic breast cancer cell line MCF-10A." (PMID 21281469, 2011). "Surprisingly, we found CTC counts to be higher in ER+ patients in comparison to HER2+ and triple negative patients, which could be explained by low EpCAM expression and a more mesenchymal phenotype of tumors belonging to the basal-like molecular subtype of breast cancer." (PMID 20838621, 2010). "EpCAM, HER2, and EGFR are the most commonly used surface markers for breast cancer CTCs and form a good foundation for the detection of CTCs." (PMID 41543394, 2026).